IL16 (interleukin 16)
Diseases named in the same sentence as IL16 in open-access papers (continued):
Sharing a sentence is not in itself a finding about the gene and the disease.
epilepsy (1 paper, 2019). A brain disorder characterized by episodes of abnormally increased neuronal discharge resulting in transient episodes of sensory or motor neurological dysfunction, or psychic dysfunction. "Activation of the NLRP3 inflammasome has been detected during epilepsy, and knockdown of NLRP3 or caspase-1 decreased IL-1β and IL-16 levels and provided neuroprotection against SE-associated neuronal damage." (PMID 31097691, 2019).
esophagitis (1 paper, 2025). An acute or chronic inflammatory disease affecting the esophageal wall. "Reduced severity of esophagitis was associated with downregulation of EGF, IL-16, CCL3, CCL7, and prolactin, suggesting decreased inflammation." (PMID 39808500, 2025).
fibromyalgia (1 paper, 2025). A chronic disorder of unknown etiology characterized by pain, stiffness, and tenderness in the muscles of neck, shoulders, back, hips, arms, and legs. "Based to the finding of the current study on association of IL-16 and fatigue-fibromyalgia symptoms, one could hypothesize that high IL-16 levels could stand for fatigue symptoms common in patients with other autoimmune, inflammatory diseases or even cancer, and coins further studies." (PMID 40529362, 2025).
fungal infection (1 paper, 2022). "The cytokines of MIP-1β, IL-8, and IL-16 played important roles in recruiting macrophages, neutrophils, and CD4 molecules, respectively, which are crucial immune cells against fungal infection." (PMID 35252030, 2022).
gallstones (1 paper, 2025). Solid crystalline precipitates in the biliary tract, usually formed in the gallbladder, resulting in the condition of cholelithiasis. "For example, gallstone patients had higher levels of IL‐6, IL‐10 and IL‐12p70 than population‐based controls, and GBC patients had increased levels of C‐reactive protein (CRP), CCL20, IL‐16, sTNFRI and sTNFRII compared to gallstones controls." (PMID 39482824, 2025).
gestational diabetes (1 paper, 2019). Carbohydrate intolerance first diagnosed during pregnancy. "Furthermore, a remarkably decreased frequency of IL-16 rs4778889 CC genotype has been detected in women with gestational diabetes mellitus (GDM), suggesting the genetic role of IL-16 polymorphisms in GDM." (PMID 31375554, 2019).
glioblastoma (1 paper, 2025). The most malignant astrocytic tumor (WHO grade IV). "Glioblastoma cell-derived EVs upregulated the expression of the pro-tumor genes in microglia cells, including the CXCL1/10, CCL2/CCL5, and IL-6, and downregulated immune response-associated genes, such as IL-16, IL-23, and IL-2740." (PMID 39781357, 2025).
Granuloma (1 paper, 2020). A compact, organized collection of mature mononuclear phagocytes, which may be but is not necessarily accompanied by accessory features such as necrosis. "Regarding that the PR3-ANCA is more relevant in GPA than in MPA, there is a possibility of IL-16 being associated with granuloma." (PMID 32264927, 2020). "One possible explanation for this phenomenon is that IL-16 could play a role in causing granuloma." (PMID 32264927, 2020).
hemorrhagic fever (1 paper, 2017). An infectious disease caused by certain viruses or bacteria that can damage the walls of tiny blood vessels, making them leak, and can hamper the blood's ability to clot and cause severe, life-threatening illness. "Hemorrhagic fever with renal syndrome cases were characterized by a strong expression of MIF, IL-12p40, IL-3, IL-16, CXCL9, CCL27, CXCL1, and HGF." (PMID 28572804, 2017).
Hyperglycemia (1 paper, 2019). An increased concentration of glucose in the blood. "Instead, salivary gland dysfunction was associated with hyperglycemia and elevation of serum IL1β, IL16, and CXCL13." (PMID 31784615, 2019).
hypothyroidism (1 paper, 2023). Abnormally low levels of thyroid hormone. "Conversely, when we treated hypothyroidism as an exposure factor, we detected a causal association between hypothyroidism and 13 inflammatory cytokines (IL-13, IL-16, IL-2rα, IL-6, IL-7, IL-9, G-CSF, SCGF-β, IP-10, MIG, MIP-1β, SDF-1α, and TNF-α)." (PMID 38317717, 2023).
Kawasaki disease (1 paper, 2022). A rare inflammatory disease characterized by an acute febrile, systemic, self-limiting, medium-vessel vasculitis primarily affecting children. "Compared with other datasets, it was confirmed that IL-16 increased uniquely in the patient with BNT162b2-MyoC, and CXCL also increased in both patients with Kawasaki disease and CoV2-MyoC." (PMID 36225942, 2022).
kidney damage (1 paper, 2023). "Since IL-16 and CCL3 are both potent chemoattractants for T and NK cells and known molecules involved in cell-mediated kidney damage, this indicates a distinct role of the suPAR molecule for kidney tissue inflammation and subsequent organ damage." (PMID 37036003, 2023).
kidney failure (1 paper, 2024). An acute or chronic condition that is characterized by the inability of the kidneys to adequately filter the blood. "We conclude that the cytokine IL-16 correlates with plasma oxalate concentrations and is substantially increased in patients with kidney failure on dialysis." (PMID 38760468, 2024).
lentivirus infection (1 paper, 2016). Virus diseases caused by the Lentivirus genus. "The increased IL-16 expression during the lentivirus infection might therefore have inhibited viral integration." (PMID 27399757, 2016).
lipoma (1 paper, 2008). A benign, usually painless, well-circumscribed lipomatous tumor composed of adipose tissue. "At focal adhesions the C-terminal SH3 domain of LASP-1 is involved in protein-protein interactions through binding to proline-rich sequences, specifically with palladin, lipoma preferred partner (LPP), Prointerleukin-16 (Pro-IL-16), vasodilator stimulated phosphoprotein (VASP) and zyxin." (PMID 18419822, 2008).
liver cancer (1 paper, 2023). An epithelial or non-epithelial malignant neoplasm that arises from the liver. "It was previously reported that SOR reduces TNF-α and IL-16 levels in liver cancer in vitro." (PMID 37259369, 2023).
liver failure (1 paper, 2015). A liver disease characterized by the liver losing or has lost all of its function. "It is also interesting to note that ADIPOQ, β-NGF, CXCL1, CXCL9, CXCL12, IL-16, and PECAM-1 are up-expressed only in those CHC and HCC patients who present a liver failure, and, hence, linkable to the necro-inflammatory activity of the liver." (PMID 26226632, 2015).
lung adenocarcinoma (1 paper, 2018). A carcinoma that arises from the lung and is characterized by the presence of malignant glandular epithelial cells. "Stratified analyses for pathological type suggested a significant association of IL-16 rs859 with both lung adenocarcinoma and lung small cell carcinoma." (PMID 30671474, 2018).
lung squamous cell carcinoma (1 paper, 2025). "CD28 expression on CD39+ CD4+ T cells was positively correlated to lung squamous cell carcinoma (LUSC) risk (OR, 1.0335 [95% CI, 1.009–1.0586]), inversely mediated by IL-16 (95% CI, −0.01 to −0.0003)." (PMID 41292522, 2025).
lupus erythematosus (1 paper, 2025). An autoimmune, connective tissue chronic inflammatory disorder affecting the skin, joints, kidneys, lungs, heart, and the peripheral blood cells. "Lately, two independent groups identified IL-16 as the key cytokine in cutaneous and renal involvement in lupus erythematosus, and also in mouse model of SLE-like pulmonary inflammation." (PMID 40529362, 2025).
lymphoma (1 paper, 2025). A malignant (clonal) proliferation of B- lymphocytes or T- lymphocytes which involves the lymph nodes, bone marrow and/or extranodal sites. "It is driven by lymphoma-derived IL-16 and additionally CCL5 chemokine." (PMID 41219641, 2025).
medulloblastoma (1 paper, 2017). A malignant, invasive embryonal neoplasm arising from the cerebellum. "In cultured medulloblastoma spheres, only IL-8, IL-16 and VEGFA were detected." (PMID 28417956, 2017).
melancholia (1 paper, 2024). A subtype of depression characterized by the inability to find pleasure in positive things combined with physical agitation, insomnia, or decreased appetite. "We found that 53.2% of the variance in melancholia was explained by the regression on IL-16 and SCGF (both positively) and CCL3 (inversely)." (PMID 38538641, 2024).
membranous nephropathy (1 paper, 2024). "The urinary and plasma levels of interleukin-16 (IL-16) in patients with proliferative LN are higher than in those with mesangial proliferative LN and membranous nephropathy." (PMID 39104393, 2024).
meningioma (1 paper, 2023). A generally slow growing tumor attached to the dura mater. "Genetically predicted meningiomas were associated with levels of interleukin-16 (IL-16) (BETA = −0.037, 95% CI = −0.069 ~ −0.004) and interferon gamma-induced protein 10 (IP10) (BETA = 0.036, 95% CI = 0.003–0.068) using IVW methods." (PMID 37425011, 2023). "Moreover, Meningiomas could cause lower levels of interleukin-16 and higher levels of CXCL10 in the blood." (PMID 37425011, 2023). "Our research findings indicate that meningiomas lead to a decrease in IL-16 levels, although the evidence regarding the relationship between meningiomas and IL-16 is limited." (PMID 37425011, 2023). "In summary, the alterations in IL-16 and IP-10 levels in the blood of meningioma patients indicate complex interactions between tumors and the immune system." (PMID 37425011, 2023). "We speculate that the decrease in IL-16 levels may suggest the presence of similar immunosuppressive mechanisms in the meningioma microenvironment, which contribute to tumor growth and evasion of immune surveillance." (PMID 37425011, 2023). "Meningiomas also affect the expression of cytokines such as IL-16 and CXCL10." (PMID 37425011, 2023).
mood changes (1 paper, 2023). "Initial Kaplan–Meier methods found that the baseline TSH values, CRP levels, IL-16 levels, and anti-TG antibody levels were associated with incidence of mood changes during follow-up." (PMID 37090700, 2023).
myeloid leukemia (1 paper, 2022). A clonal proliferation of myeloid cells and their precursors in the bone marrow, peripheral blood, and spleen. "The evidence supports the theory that dust particles can activate IL-1β, IL-16, NF-κB, and COX-2 expression in human myeloid leukemia cells, indicating strong inflammatory responses." (PMID 35723329, 2022).
Nephroblastoma (1 paper, 2014). An embryonal neoplasm characterized by the presence of epithelial, mesenchymal, and blastema components. "In contrast, levels of IL-16; IL-31; insulin receptor (IR); immunoglobulin M (IgM); Karyopherin-a2; nephroblastoma overexpressed (NovH, also known as insulin-like growth factor binding protein 9); SCF sR; TPSB2; VEGF sR2; and sL-Selectin decreased following treatment." (PMID 25100134, 2014).
oral disease (1 paper, 2025). "Previous studies have identified levels of IL‐16 in gingival crevicular fluid were increased around teeth with a periodontal inflamed surface, suggesting a harmful role in oral disease." (PMID 39777419, 2025).
Ovarian cyst (1 paper, 2018). The presence of one or more cysts of the ovary. "Occasional staining for IL-16 by malignant cells as well as cells of ovarian cysts was also seen in hens with PCOC." (PMID 30596106, 2018). "Influx of IL-16-expressing cells was detected in the vicinity of ovarian cysts in the stroma." (PMID 30596106, 2018). "In addition, influx of IL-16 was detected in close proximity of ovarian cysts in the stroma." (PMID 30596106, 2018). "Increased expression of SOD2 in ovarian cysts and tumors in PCOC hens observed in this study may be a response to the oxidative stress due to an increased infiltration of immune cells (macrophages and IL-16-expressing cells) in polycystic ovaries and the subsequent development of PCOC." (PMID 30596106, 2018).
ovarian tumors (1 paper, 2015). "On the other hand, expression of IL-16 by the tumor epithelium and its serum levels has been reported to increase in association with ovarian tumor development." (PMID 26161406, 2015). "Moreover, similar to humans, expression of IL-16 by ovarian tumors has been reported to be increased in association with tumor development and progression in hens." (PMID 26161406, 2015). "This study examined, for the first time, suitability of IL-16-targeted contrast agent, a newly developed ultrasound imaging agent, in improving the in vivo visualization of ovarian tumors in laying hens, a preclinical model of spontaneous OVCA." (PMID 26161406, 2015). "Overall, the results of the present study suggest that the IL-16-targeted contrast agents bind with their targets expressed by the spontaneous ovarian tumors in hens and enhance the visualization of tumors at early and late stages." (PMID 26161406, 2015). "Compared with precontrast scanning, IL-16-targeted contrast enhanced imaging improved the visualization of ovarian tumor masses in these 23 hens on gray scale." (PMID 26161406, 2015). "The results of this study demonstrated that IL-16-targeted contrast imaging agents bound with their targets expressed by ovarian tumors at early and late stages in hens and enhanced the intensities of ultrasound imaging signals from these tumors." (PMID 26161406, 2015). "Increases in signal intensities due to IL-16-targeted contrast imaging were positively correlated with the frequencies of IL-16 expressing microvessels in ovarian tumors at early stage (r = 0.46) and late stage (r = 0.70)." (PMID 26161406, 2015). "The goal of this study was to examine the feasibility of IL-16-targeted contrast agents in enhancing the intensity of ultrasound imaging from ovarian tumors in hens, a model of spontaneous OVCA." (PMID 26161406, 2015). "In this study, compared with precontrast, IL-16-targeted contrast enhanced imaging increased the ultrasound signal intensity remarkably from hens with ovarian tumors at both early and late stages." (PMID 26161406, 2015). "Presently, studies with hens are ongoing in which animals are being monitored prospectively with IL-16-targeted contrast agents together with serum IL-16 levels to detect spontaneous ovarian tumor development at relatively earlier stages." (PMID 26161406, 2015). "Thus IL-16 expressing cells in ovarian tumors represent a potential target for ultrasound imaging for noninvasive detection of OVCA at early stage provided a targeted imaging agent is developed." (PMID 26161406, 2015). "Therefore, the goal of this study was to examine whether IL-16-targeted contrast agents enhance the intensity of traditional TVUS imaging and improve the early detection of spontaneous ovarian tumors in laying hens, a preclinical model of OVCA." (PMID 26161406, 2015).
polycystic ovaries (1 paper, 2018). "This study showed that, compared with normal ovaries, the frequencies of macrophages and IL-16- (a proinflammatory and chemotactic cytokine-) expressing cells were higher in polycystic ovaries with cancer at the early stage and late stage." (PMID 30596106, 2018).
pregnancy disorder (1 paper, 2015). A disorder that is related to pregnancy. "It has been suggested that increased secretory mature form of IL16 production by trophoblasts contributes to the altered balance in the immune-inflammatory responses often associated with pregnancy disorder." (PMID 26546156, 2015).
Premature rupture of membranes (1 paper, 2025). Premature rupture of membranes (PROM) is a condition which occurs in pregnancy when the amniotic sac ruptures more than an hour before the onset of labor. "IL-16 is a cytokine actively involved in the inflammatory response, and its role in conditions like preterm birth or premature rupture of membranes (PROM) has been the objective of research." (PMID 41375625, 2025).
pulmonary congestion (1 paper, 2013). "Atrial weight and lung weight were also decreased by IL-16 neutralization, suggesting that IL-16 neutralization might have inhibited the increase in LV filling pressure and pulmonary congestion." (PMID 23894370, 2013).
pulmonary disorders (1 paper, 2024). "The blockade of eotaxin and IL-16 causes 70% inhibition of eosinophil chemotactic activity to the lung in pulmonary disorders." (PMID 38133713, 2024). "Collectively, these studies suggest that bronchial and alveolar epithelial cells secrete cytokines, such as IP-10, IL-16, or eotaxin, leading to subsequent pulmonary disorders, consistent with our in vitro experiments." (PMID 38133713, 2024).
retinal detachment (1 paper, 2020). An eye emergency condition which may lead to blindness if left untreated. "The concentrations of HGF, IFN-gamma, IL-6, IL-16, MIF, MCP-1 were significantly higher in all groups of retinal detachment compared to controls." (PMID 32542038, 2020). "Levels of HGF, IL-6, IL-8, IL-16, IFN-gamma, MCP-1, and MIF were significantly higher in all groups of retinal detachment compared to ERM." (PMID 32542038, 2020). "Levels of HGF (p<0.0001), IFN-gamma (p<0.0001), IL-6 (p<0.0001), IL-16 (p<0.0001), MIF (p<0.0001), MCP-1 (p<0.0001) were significantly higher in all groups of retinal detachment compared to the group of ERM." (PMID 32542038, 2020).
sarcoma (1 paper, 2025). A usually aggressive malignant neoplasm of the soft tissue or bone. "Levels of IL-1β, IL-4, IL-6, CXCL5, CXCL12, CXCL14, MIF, IGF-1, TGFβ-1, and CCL21 were increased in one or more sarcoma cohorts compared with controls, and levels of IL-15 and IL-16 were significantly lower in one or more sarcoma cohorts compared to healthy controls." (PMID 41008853, 2025).
SARS-CoV infection (1 paper, 2021). "SARS-CoV infection increases cytokine expression (e.g., IFN-γ, IL-1, IL-6, IL-10, IL-12, and IL-16) dramatically, and T lymphocytes and their CD4+ and CD8+ T cells subsets are decreased after the onset of infection." (PMID 33770147, 2021).
Sciatica (1 paper, 2024). Pain in the lower back and hip radiating in the distribution of the sciatic nerve. "For instance, several key chemokines including CCL2, CCL11, CXCL5, CXCL6, and IL-16 were positively associated with sciatica." (PMID 39015317, 2024).
secretory otitis media (1 paper, 2024). "It has recently been shown, in secretory otitis media (SOM), that different inflammatory mediators, such as CXCL1, IL-16, IL-8, IL-17, IL-1β, CXCL10, and CXCL9, were found in high concentrations in middle ear fluids, in association with the presence of bacterial and viral nucleic acid levels." (PMID 38541021, 2024).
silicosis (1 paper, 2023). Silicosis is a respiratory disease caused by breathing in (inhaling) silica dust. "Patients with silicosis seem to have a chronic inflammatory process that is consistent with the augmented levels of some pro-inflammatory cytokines, i.e., IL-1β, IL-6, IL-7, IL-8, IL-16, IL-17A, IL-33 and TNF-α were observed in this work." (PMID 36675056, 2023).
streptococcal infection (1 paper, 2017). Any of the several infectious disorders caused by members of streptococcus, a genus of gram positive bacteria belonging to the family Streptococcaceae. "In this context, Vγ9/Vδ2 T cells and TNF-α appear to be particularly relevant in Gram-negative infections, IL-1β and MMPs in streptococcal infections, and IL-16 and sIL-6R in CNS infections." (PMID 28318629, 2017).
T-cell leukemia (1 paper, 2023). A malignant disease of the T-lymphocytes in the bone marrow, thymus, and/or blood. "Positioned at the center of the SN-Treg signaling network, IL16 can attract CD4+ T cells and inhibit CD3-mediated lymphocyte activation and proliferation, and recombinant human IL16 has shown inhibitory effects on the growth of human T-cell leukemia Jurkat cells." (PMID 38054018, 2023).